LAG3 (lymphocyte activating 3)
Diseases named in the same sentence as LAG3 in open-access papers (continued):
Sharing a sentence is not in itself a finding about the gene and the disease.
cancer (continued). "Examples include ImmTAC® molecules, which are engineered to recognise intracellular cancer antigens with ultra-high affinity and selectively target these cancer cells via an anti-CD3 immune-activating effector function, and could be combined with LAG-3 inhibitors." (PMID 37072748, 2023). "Consequently, this indicates a negative prognostic value of LAG3 across different cancer types." (PMID 38041068, 2023). "Additionally, FGL-1 is the main immune ligand of lymphocyte-activation gene 3 (LAG-3) that negatively regulates T cells’ activation and plays a vital role in hepatocyte regeneration, glucose and lipid metabolism, as well as serving as a potential target for cancer immunotherapy." (PMID 36556955, 2022). "Therefore, clinically meaningful cancers have several mechanisms involved in immunosuppression, such as enhancing different cells to participate in immunosuppression and enhancing various molecules to participate in immunosuppression, including CTLA4, PD1, PDL1, LAG3 and other immune checkpoints." (PMID 33557848, 2021). "Indeed, animal models of chronic viral infection and cancer have demonstrated that PD1+LAG3 combination blockade is more effective than either alone, and of the 33 ongoing registered clinical trials of LAG3-blockade, all but two are testing LAG3+PD1 combination blockade." (PMID 30653605, 2019). "The synergistic, non-redundant effects of blocking both LAG-3 and PD1 have also been further described in mouse models of cancer, where deletion of these inhibitory receptors in CD8+ T cells resulted in enhanced effector function." (PMID 40299510, 2025). "In contrast, no clinical evidence is available for anti-LAG3, anti-TIGIT, anti-BTLA, anti-ICOS and anti-IDO1 antibodies in MSI-H cancers, but clinical trials are ongoing." (PMID 38254772, 2024). "Interestingly, the combination of LAG-3 blockade with PD-1 blockade exhibited a stronger antitumor efficacy than either treatment alone, suggesting that LAG-3 could be a potential therapeutic target for combination therapies with PD-1 blockade in MHC-II expressing cancers." (PMID 35008422, 2022). "Regarding gene expression, cancer immune evasion-related genes were found up-regulated in the negative BL samples, such as CD274 (alias PD-L1), IDO1, LAG-3, CTLA4, and CD80 and CD86 genes, required for the activation of the inhibitory activity of CTLA4." (PMID 34680332, 2021). "However, there are many other proteins, such as lymphocyte activation gene-3 (LAG-3, CD223), B and T cell lymphocyte attenuator (BTLA, CD272), T cell immunoglobulin-3 (TIM-3), etc., which play important roles in the immune response to cancer, although their mechanisms of action remain unclear." (PMID 32018226, 2020). "It was identified that HAVCR2 had positive infiltration scores in all cancer types, whereas a negative infiltration score was noted for CXCL13 (in LGG and DLBCL), LAG3 (in DLBCL and AML), LAYN (in CHOL, KICH, AML, LGG, PCPG, THCA and UCS), PDCD1 (in DLBCL, AML and THYM) and TIGIT (DLBCL and AML)." (PMID 40076932, 2025). "Our analysis of LRRC59 in relation to pan-cancer immune infiltration and immunotherapy reveals a positive correlation between LRRC59 expression and TIM-3 and TIGIT, while a negative correlation with LAG-3 and PDCD1." (PMID 38738999, 2024). "CD8+ cells infiltrating cancer-cell islets featured higher expression of proteins related to effector function (GZMB, CD127), T-cell co-stimulation and co-inhibition (PD-1, LAG3, 4-1BB, GITR, STING, B7-H3), and other non-T-cell co-inhibitory proteins (PD-L1, PD-L2), IDO1, and Ki-67." (PMID 38044986, 2023). "Given the inhibitory effect of LAG3 and FGL1 on the immune response, these oncogenes may predict a negative prognosis in several cancers." (PMID 35111155, 2021).
cancer (continued). "A contrary hypothesis is that efficacy of anti-PD1/L1 and anti-LAG3 may, in fact, be due to their anti-cancer rather than immune modulatory effects, in which case anti-PD1/L1 plus another anti-cancer therapy would be preferable over anti-PD1/L1 plus another immune activating/modulatory therapy." (PMID 38539487, 2024). "Thus, although NK cells might be important players that contribute to the anti-tumor activity of IC inhibitors (ICIs) like antibodies against CTLA-4, LAG3, and the PD1/PD-L1 axes in cancer patients, this should not overestimate the function of some T cell-ICs in healthy NK cells." (PMID 31998304, 2019).
infection (109 papers, 2013 to 2026). The state of being infected such as from the introduction of a foreign agent such as serum, vaccine, antigenic substance or organism. "To understand the influence of Tr1 cells on the systemic response to infection, we quantified the abundance of Tr1-associated molecules (granzyme A, IFNγ, IL-10, and LAG3) in plasma from the same blood samples used to study CD4+ T cells as a part of MUSICAL." (PMID 41000872, 2025). "HMPV infection causes an increase in LAG-3 expression, possibly as a protective regulatory response." (PMID 36680187, 2023). "Collectively, these results indicated that LAG3 deficiency can enhance antiparasitic immunity by limiting Th2 and Treg responses while promoting the Th1 response at a late stage after 24 weeks of infection." (PMID 37172058, 2023). "SMARTA T cells co-expressing both PD1 and Lag3 were most abundant following Clone-13 GP61 wt infection and decreased in response to Clone-13 variant infection." (PMID 33684030, 2021). "Together, VUE appears to be associated with greater infiltration of LAG3+ cells compared to infection and controls, but cells expressing CTLA4 are generally absent in the placenta from our three groups." (PMID 34394102, 2021). "Infection with Plasmodium parasites (P. yoelii 17XL, P yoelii 17XNL, P. chabaudi, P. vinckei, and P. berghei) causes increased PD-1 and LAG-3 expression by activated CD4 cells." (PMID 34067904, 2021). "Furthermore, experiments with PD-1 deficient mice demonstrated that using LAG-3 blockade during infection with hMPV can restore CD8+ T cell function, but increases pulmonary pathology." (PMID 36680187, 2023). "LAG-3 expression has also been linked to increased pathology in certain infections." (PMID 34067904, 2021). "Moreover, post-vaccine administration, the neo-epitope-specific T cell infiltrate was largely PD-1+Lag3+Tim3+, markers associated with T cell dysfunction and exhaustion in infection and cancer." (PMID 33298945, 2020). "Due to complex immune environments and severe immune-mediated liver damage often caused by these phasic infections, further study is needed to determine whether LAG3 is harmful or beneficial." (PMID 30653605, 2019). "Our data indicate that IL-10-producing Tr1 cells, Treg cells and CD8+ T cells are all capable of co-expressing LAG3 and CD49b in vitro following differentiation under IL-10-inducing conditions, and in vivo following pathogenic insult or infection in the pulmonary mucosa." (PMID 30510554, 2018). "Despite observations that LAG3 deficiency delays lesion growth by inhibiting Foxp3+ Treg and Th2 cell differentiation and promoting Th1 cell formation in the late stage of E. multilocularis infection, our data revealed a different outcome in the middle stage of infection." (PMID 37172058, 2023). "Thus, LAG3 blockade improved antiparasitic immunity in association with reduced numbers of Tr1 cells and a limited effect on the inflammatory response, as indicated by a marginal change in Th1 cell numbers at sites of infection." (PMID 37917177, 2023). "multilocularis infection, LAG3-/-CD4+ T cells exhibited a greater propensity to differentiate into CD4+ effector T (Teff) cells and produced higher levels of IFN-γ and IL-10 in both the livers and spleens of recipient mice." (PMID 41680821, 2026). "Both scRNA-seq and flow cytometry confirmed that infection markedly upregulated LAG3 on CD4+ T cells." (PMID 42192546, 2026). "Upon infection, mice with higher levels of Lag3+IL10+CD138+ plasma cells exhibit a weaker immune response, whereas mice with fewer LAG3+ plasma cells show increased levels of memory T cells, suggesting an immunosuppressive role of Lag3 in plasma cells." (PMID 41177809, 2025). "It demonstrated a significant increase in LAG-3 mRNA levels after ten weeks of infection compared to samples infected for 4 weeks, particularly expressed in T cell subpopulations." (PMID 38957797, 2024).
infection (continued). "The expression of LAG-3 was positively correlated with T cell exhaustion status and infection severity in LCMV infections." (PMID 37355637, 2023). "Furthermore, there are cases where LAG-3 is responsible for mediating T cell dysfunction, known as cell exhaustion or depletion, which are T cells characterized by a progressive loss of effector functions that can prevent optimal control of infections and tumors." (PMID 36680187, 2023). "Eight days after infection, both LCMV strains showed increased expression of genes associated with CD8+ T cell activation, such as Pdcd1, Rgs16 and Lag3, in agreement with previous findings." (PMID 37813964, 2023). "Tim3, Lag-3, 4-1BB, and to a lesser extend 2B4 are hallmarks for T cell priming post-primary infection while KLRG1 and Tigit are markers for restimulated and long lived HCMV-specific CD8T responses." (PMID 36532017, 2022). "In contrast to our results, a recent study identified a key role for PD-1 in combination with LAG-3 in maintaining memory CD8+ T cell precursors early during infection." (PMID 34326837, 2021). "During primary and secondary infections with hMPV, the expression levels of LAG3 were upregulated, as also seen for the receptor TIM3." (PMID 33809875, 2021). "In fact, CD11ahi CD49dhi CD4 T cells express PD-1 and LAG-3 during infection with Plasmodium parasites." (PMID 34067904, 2021). "In agreement with this, lymphocytic choriomeningitis viral (LCMV) and herpes simplex virus 1 (HSV-1) infections also showed an increase in LAG-3 expression after infection." (PMID 34067904, 2021). "The ability of CD4 T cells to produce cytokines deteriorated with prolonged infection, while dual blockade of PD-1 and LAG-3 with monoclonal antibodies restored the number of parasite specific CD4 T cells and their ability to secrete cytokines." (PMID 32793231, 2020). "Half of the rabbits (Group-1; n = 10) were treated with a combination of blocking α-PD-1 and α-LAG-3 mAbs, injected intravenously (i.v.)on days -3, -5, -7 before infection and then on days 3, 5, and 7 post-infection (p.i.)at 200 μg/dose." (PMID 32796943, 2020). "In chronic LCMV infection, LAG-3 expression is co-expressed with PD-1 on exhausted/dysfunctional virus-specific CD8+ T cells, and it is closely associated to the severity of infection." (PMID 33027962, 2020). "Mice were intraperitoneally (i.p.)injected with 200 μg of anti-LAG-3 mAb (n = 10) and 200 μg of anti PD-1 mAb (n = 10) at 3 different time points [i.e., days 3, 5, and 7 post-infection (PI)]." (PMID 30619285, 2018). "In spleen,Lag3 was the only inhibitory receptor that remained elevated over the entire course of infection." (PMID 30542664, 2018). "The frequency of CD4+ T cells expressing both LAG3 and CD49b (Tr1 cells) increased with infection and was further enhanced by bpV(phen) treatment." (PMID 28710387, 2017). "Furthermore, the progeny of the T-bet reporter-sorted CD4+ T cells showed high expression of the inhibitory receptors PD-1 and LAG3 already 7 days post infection with LCMV Cl13." (PMID 41488650, 2025). "Also, clusters rich in Cd44, indicative of T cell activation, Tbx21, highlighting the TH1-dominated immune response after LCMV infection, and Lag3, an early exhaustion marker, were only present after infection." (PMID 41094201, 2025). "In addition, TIM-3 and CTLA-4 were also mildly elevated and LAG-3 was decreased early in the infection in critically ill patients." (PMID 39355257, 2024). "However, there were significant increases in the percentages of CD4+ T cells and CD4+ Tem cells in spleens from LAG3-KO mice after 12 weeks of infection." (PMID 37172058, 2023). "Based on this information, it could be suggested that during infection with hRSV, the expression of LAG-3 also increases to inhibit the activation of CD8+ T cells." (PMID 36680187, 2023).
infection (continued). "LAG3 deficiency increased IFN-γ and decreased IL-4 secretion by T cells, but we did not observe significant alterations in Foxp3+ Treg differentiation and function, which led to failure to inhibit the growth of metacestodes in the middle stage of infection." (PMID 37172058, 2023). "Interestingly, LAG-3 blockade can restore cytokine production, suggesting the crucial involvement of LAG-3 during the infection with hMPV." (PMID 36680187, 2023). "Thus Tim3, Lag-3, 4-1BB and 2B4 are hallmarks for T cell priming post-primary infection, and restimulaion for 2B4, while KLRG1 and Tigit are markers for restimulated and long lived HCMV-specific CD8T cells responses." (PMID 36532017, 2022). "Conversely, Tfh module scores were generally similar between acute and chronic LCMV CD4+ T cell clusters, although the Ly6c2-hi Th1 and Lag3-hi Th1 cell subsets from chronic LCMV infection did display a relatively increased Tfh signature compared to their acute infection counterparts." (PMID 36255051, 2022). "LAG-3 was shown to be highly upregulated on exhausted CD8+ T cells during LCMV Cl 13 infection." (PMID 34696381, 2021). "Additionally, C57BL/6J mice undergo T cell exhaustion during infection with T. gondii, and during Plasmodium infection, PD-L1 and LAG3 blockade improves germinal center and plasma cell responses via an enhanced T follicular help." (PMID 34871323, 2021). "Importantly, dual blockade of PD-1 and LAG-3 led to a significant increase in the functionality of antiviral CD8+ T cells during LCMV Cl 13 infection." (PMID 34696381, 2021). "Interestingly, the in vitro blockade of PD-1/LAG-3 interactions enhanced cytokine production in response to infection." (PMID 34067904, 2021). "Additionally, we observed significantly higher counts of PD-1+ (>100 cells/image) and LAG3+ (0-120 cells/image) cells infiltrating into the villi during VUE compared to infection and control." (PMID 34394102, 2021). "While it is unknown whether levels of FGL-1 increase during malaria infection, an appealing hypothesis may be that FGL-1 contributes to inhibiting LAG-3 expressing subsets of T cells during infection, including CD8+ T cells." (PMID 33519801, 2020). "In chronic infection models, LAG3 expression was directly correlated with infection severity." (PMID 31434339, 2019). "LAG-3+CD8+ T and PD-1+CD8+ T cells increased in both TG and cornea as early as 3 days of acute infection, and on day 14-post-infection (just after the acute infection has cleared), there were significantly more LAG-3+CD8+ T cells and PD-1+CD8+ T cells in both the cornea and TG." (PMID 30619285, 2018). "Still, LAG3 up-regulation could reflect persistent immune activation of T cells during infection, which is supported by the finding that LAG3 expression decreased again in HIV-infected individuals on successful ART." (PMID 29987244, 2018). "It has been shown that blockade of PD-L1 and LAG-3 rapidly cleared infection with plasmodia, indicating that during infection this loop is operative and could be manipulated." (PMID 26539181, 2015). "LAG3 deficiency further enhanced the production of interferon-y (IFN-γ), IL-4, and IL-10 by splenic CD4+ T cells in the initial infection phase, which may contribute to the slight suppression of E. multilocularis growth and development observed in the livers of LAG3-knockout mice." (PMID 41680821, 2026). "Therefore, the increased LAG-3 expression observed in individuals who later experienced breakthrough infection may indicate an altered immune profile, potentially indicative of early dysfunction, or reflect recent activation." (PMID 40977733, 2025). "Therefore, Foxp3+ Treg differentiation may also be mediated by molecules other than LAG3, particularly during the middle stage of infection." (PMID 37172058, 2023). "Moreover, we also assessed WT or LAG3-KO mice at 12 weeks of infection." (PMID 37172058, 2023).